RET (ret proto-oncogene)
Diseases named in the same sentence as RET in open-access papers (continued):
Sharing a sentence is not in itself a finding about the gene and the disease.
breast carcinoma (continued). "RET expression is more common in estrogen receptor positive (ER+ve) tumors, which are the most common breast cancer subtype, but it is also detected in other subtypes." (PMID 30666215, 2018). "Several studies, combining inhibitors of RET and mTOR signaling (e.g., everolimus) have shown increased or prolonged benefit over single agents in thyroid and breast cancer models." (PMID 30666215, 2018). "The landscape of RET genomic alterations in 9693 breast cancer samples was assessed as part of hybrid capture-based next-generation sequencing of up to 405 cancer-related genes including select introns of up to 25 genes (gene panels)." (PMID 30446652, 2018). "With new evidence of the presence of oncogenic, recurrent RET fusions and rearrangements in breast cancer, clinical trials catering to RET-rearranged cancers need to be expanded to evaluate these selected breast cancers." (PMID 30446652, 2018). "We suggest that RET-mediated endocrine resistance occurs when ER+ breast cancer cells express the RET ligand GDNF." (PMID 29608602, 2018). "In this study, RET alterations are reported from a large cohort of 9693 breast cancers that were genomically profiled as part of routine clinical care." (PMID 30446652, 2018). "Overall, our study provides insights into how the RET signaling pathway become activated in ER+ breast cancers." (PMID 29608602, 2018). "RET alterations, identified by genomic profiling, are promising therapeutic targets and are present in a subset of breast cancers." (PMID 30446652, 2018). "Elevated levels of RET receptors are found in different subtypes of human breast cancers, and high RET correlates with decreased metastasis-free survival." (PMID 27092013, 2016). "Results obtained from The Cancer Genome Atlas Network for both colorectal and breast cancer showed the co-existence of mutations in these genes, although in low proportions (4.93% for PIK3CA and KIT and 1.23% for KIT and RET)." (PMID 26968814, 2016). "We have demonstrated previously that increased GDNF/RET signaling in ER+ breast cancers promotes AI resistance." (PMID 27602955, 2016). "In this study, we demonstrate that NVP-AST487 and NVP-BBT594 have comparable potencies as inhibitors of GDNF-induced RET signaling in ER+ breast cancer cells in vitro." (PMID 27602955, 2016). "There is also evidence supporting the premise that RET/PTC is an estrogen-dependent gene required for breast cancer cell growth." (PMID 26918339, 2016). "More recently, RET has been involved in other forms of neoplasia including lung, pancreatic and breast cancers, thus demonstrating expanded oncogenic potentialities." (PMID 27034161, 2016). "Taken together these two studies, using distinct in vivo breast cancer models, indicate that RET signaling in tumor cells in vivo promotes tumor growth." (PMID 27602955, 2016). "TFAP2C has been shown to induce ER independent RET expression, with important implications for the ER-ve breast cancers, such as MDA-MB-453." (PMID 27034161, 2016). "In these experiments it is important to note that there was no exogenous GDNF treatment indicating that in an in vivo setting RET signaling is active in these ER+ breast cancer xenografts." (PMID 27602955, 2016). "Accordingly, the combination of the AI letrozole with the RET inhibitor NVP-BBT594 is more effective at suppressing GDNF-induced proliferation of RET+ ER+ breast cancer cells than either monotherapy." (PMID 27602955, 2016). "We, along with others, have reported that the receptor tyrosine kinase RET plays an important role in endocrine therapies resistance in ER+ breast cancer cells by promoting ER phosphorylation, cell proliferation, and cell survival." (PMID 27602955, 2016). "Luminal-type breast cancer cells (e.g., MCF-7 and T47D) express RET (a proto-oncogene which encodes for a receptor tyrosine kinase for members of the glial cell line-derived neurotrophic factor) and leukemia inhibitory factor (LIF)." (PMID 26243145, 2015).
breast carcinoma (continued). "The contrasting effects of expression on clinical outcome in high RET breast cancers support the role of Cbl-c as a negative regulator of RET signaling and of Enigma opposing this action and potentiating RET signaling." (PMID 24466333, 2014). "Its selectivity and differential target profile make SPP86 an additional useful inhibitor for studies on RET function in human breast cancer cell lines." (PMID 25409876, 2014). "To assess the effects of Enigma and Cbl-c expression on outcomes in patients whose tumors express RET, we combined two publicly available breast cancer datasets for which RET, Cbl-c and Enigma expression and outcome data were available." (PMID 24466333, 2014). "This novel observation needs to be considered to completely understand the role of RET in breast cancer." (PMID 24467886, 2014). "RET interacts functionally with ERα to promote breast cancer cell proliferation and is frequently overexpressed in ERα positive breast cancer." (PMID 25409876, 2014). "Consistent with these biochemical data, exploratory analyses of breast cancer patients with high expression of RET suggest that high expression of Cbl-c correlates with a good outcome, and high expression of Enigma correlates with a poor outcome." (PMID 24466333, 2014). "RET (rearranged during transfection) is a receptor tyrosine kinase overexpressed in a subset of oestrogen receptor (ER)-positive breast cancers whose expression is regulated by ER signalling." (PMID 24467886, 2014). "We thus evaluated the utility of using SPP86 to interrogate RET signaling in MCF7 breast cancer cells." (PMID 25409876, 2014). "Further study is needed to investigate the role of MYBL1 and RET in estrogen induced breast cancer development." (PMID 23305139, 2013). "Considering breast cancer, RET copy number gains have been documented and RET mutations and rearrangements have been reported at low frequencies; however, these have not been examined for transforming ability." (PMID 23868506, 2013). "RET is over-expressed in breast cancer ERα-positive breast cancer, and its activation stimulates MCF-7 breast cancer cell proliferation, survival and scattering." (PMID 21978374, 2011). "A direct link between RET and HR expression has not yet been made; however, RET is observed to be elevated in ER+ luminal B breast cancers, which historically have loss of PR." (PMID 39000231, 2024). "Furthermore, RET expression correlates with ER expression in breast cancer cell lines and tumor specimens." (PMID 39931212, 2024). "Ongoing clinical trials with RET-inhibitors enrolling breast cancer patients." (PMID 39211557, 2024). "Estrogen responsive transcriptional enhancers in RET were described in connection with breast cancer and may play a role in the observed sex differences for PPGL." (PMID 38481600, 2024). "The clinical relevance of RET expression in ER+ breast cancer was investigated by gene array analysis of primary tumors treated with endocrine therapy and by immunohistochemical scoring of metastatic lesions from patients who received combined CDK4/6i and endocrine therapy." (PMID 39931212, 2024). "Finally, we show that clinical ER+ breast cancer samples expressing high mRNA levels of RET correlated with poor clinical outcomes following endocrine therapy." (PMID 39931212, 2024). "Published clinical trials with RET-inhibitors including breast cancer patients." (PMID 39211557, 2024). "Finally, we evaluated the clinical relevance of RET by assessing the correlation between RET expression and clinical outcomes in ER+ breast cancer patients." (PMID 39931212, 2024). "Nevertheless, the ways RET alterations could impact the prognosis of breast cancer and its response to treatment remain only partially elucidated." (PMID 39211557, 2024).
breast carcinoma (continued). "Finally, analysis of RET expression in ER+ breast cancer patients treated with endocrine therapy showed that high RET expression correlated with poor clinical outcomes." (PMID 39931212, 2024). "Our findings show that RET is overexpressed in ER+ metastatic breast cancer resistant to combined CDK4/6i and endocrine therapy, rendering RET inhibition a promising therapeutic approach for patients who experience disease progression on combined CDK4/6i and endocrine therapy." (PMID 39931212, 2024). "Overexpression of RET alone has been shown to increase growth of ER+ breast cancers in mice." (PMID 39931212, 2024). "Additionally, the recent discovery of RET enrichment in breast cancer brain metastases suggests a role for RET inhibition specific to advanced disease." (PMID 36918928, 2023). "To date, there are relatively few studies of breast cancer-specific RET alterations." (PMID 36918928, 2023). "Notably, many Luminal B-like breast cancer cell lines are among those with the highest levels of RET mRNA expression, according to publicly available datasets, though the function of RET outside ER+, HER2− breast cancer has yet to be examined in detail." (PMID 36918928, 2023). "Among these mechanisms, RET signaling has been implicated in other cancers as well as breast cancer resistance, however, the mechanism behind how RET signaling promotes resistance in ERα+ BC has not been previously studied." (PMID 36765275, 2023). "Given the frequency and clinical significance of bone metastases from breast cancer, the emergence of a RET fusion in a metastatic lesion of this type may also be a worthwhile area for future investigation." (PMID 36918928, 2023). "However, the relationship between RET and inflammation in breast cancer remains an understudied area, urgently warranting further investigation." (PMID 36918928, 2023). "Taken together, the studies above suggest that while infrequent in breast cancer, RET aberrations may present a promising therapeutic opportunity." (PMID 36918928, 2023). "While the clinical portion of this study is inherently limited due to the inclusion of only one patient, these results highlight the potential efficacy of RET inhibition, and the need for increased surveillance of RET alterations in breast cancer primary tumors and recurrences." (PMID 36918928, 2023). "For instance, sorafenib is a multikinase inhibitor involved in impairing the autophosphorylation of receptor tyrosine kinases such as VEGFR1, 2, and 3, PDGFRβ, and RET as these receptor tyrosine kinases typically involved in angiogenesis and tumor progression even in breast cancers." (PMID 37910519, 2023). "In addition, we lacked a comparison between in-house testing and CGP for KRAS/G12C, RET mutations, and NTRK rearrangements in NSCLC; and for PIK3CA mutations in breast cancer." (PMID 36832270, 2023). "RET is a key node in multiple breast cancer signaling networks." (PMID 36918928, 2023). "(2008) determined that RET and ERα pathway share a functional crosstalk in luminal breast cancer cells and RET expression can be enhanced upon stimulation of the ERα pathway, suggesting that RET-positive luminal breast cancers may benefit from RET inhibition." (PMID 35957881, 2022). "RET protein is expressed in HER2-enriched breast cancers and triple-negative breast cancers." (PMID 35957881, 2022). "Since vandetanib may provide a therapeutic effect in luminal breast cancer, AP-2γ may also be used to predict the response to vandetanib treatment, together with epidermal growth factor receptor and RET." (PMID 36197225, 2022). "A recent study identified increased expression of RET in breast cancer brain metastases (BCBM) relative to matched primary breast tumors, and that treatment of these BCBM tissues with MKI cabozantinib reduces RET activation, inhibits BCBM growth, and concurrently induces apoptosis." (PMID 35957881, 2022).
breast carcinoma (continued). "Notably, another study revealed that AP-2γ regulated epidermal growth factor receptor and receptor tyrosine kinase (RET) expressions mediate the response to vandetanib in luminal breast cancer." (PMID 36197225, 2022). "RET and co-receptor GFRα1 are overexpressed in 25-75% of breast cancer cases." (PMID 35957881, 2022). "As with other solid tumors types discussed here so far, the most common RET fusions detected in breast cancer are CCDC6-RET and NCOA4-RET, and their constitutive activation induces enhanced cell proliferation and survival that ultimately results in tumorigenesis." (PMID 35957881, 2022). "Moreover, patients with breast cancer having low mRNA levels of RET, MMP16, FN1, and SOX2 had better OS; however, the difference was not significant." (PMID 36601474, 2022). "Downregulation of RET increased the sensitivity of MCF-7 breast cancer cells to TAM." (PMID 36601474, 2022). "Sorafenib has been shown to exert anticancer effects both in preclinical models of tumor xenograft (such as breast cancer, colon, and non-small-cell lung) and in vitro by inhibiting TPC1 and TT growth, which carry the RET/PTC1 mutation and C634W RET, respectively." (PMID 35628540, 2022). "Inhibition of RET signaling enhances TAM sensitivity in the ER+ breast cancer." (PMID 36601474, 2022). "Additionally, we identified a significant association of genes involved in treatment response in breast cancer with genes producing splicing-derived neoepitopes (ERBB2, ESR1, TIMP1, ABCC3) or potentially depleted self-epitopes (AKT1, CCNE1, RET, TFF3)." (PMID 34529669, 2021). "Additionally, broad-based genomic profiling in patients with refractory breast cancer should be considered to identify potentially actionable alterations such as RET gene fusions." (PMID 34036231, 2021). "In breast cancer cell lines, RET/PTC was expressed mostly in EsR-positive cell lines." (PMID 32993133, 2020). "Concordantly, we found high RET expression rates in the Luminal B breast cancer subtypes." (PMID 30621641, 2019). "In light of this, further clinical trials identifying an adequate patient subgroup which might profit from RET inhibition as well as further studies investigating the impact of RET expression on patient outcome in breast cancer are clearly needed." (PMID 30621641, 2019). "RET genomic alterations were observed in 1.2% (121/9693) of breast cancer cases." (PMID 30446652, 2018). "RET and GFRα1 are expressed in approximately 30–70% of human breast cancers." (PMID 30666215, 2018). "Thus, we propose that ER+ breast cancer cells are intrinsically ‘poised’ for RET-mediated endocrine resistance by the activation of RET cell-surface receptors, but lack expression of the ligand GDNF." (PMID 29608602, 2018). "By a comparison of RNA-seq data in primary breast cancers, we show that both RET and GFRA1 correlate with expression of ESR1, suggesting that they may be targets of ERα signaling in primary tumors." (PMID 29608602, 2018). "First, GFRA1 overexpression is nearly twice as prevalent as RET, as was shown by a detailed IHC analysis in 245 breast cancers; thus, targeting GFRA1 could reach a wider range of breast cancers." (PMID 29796165, 2018). "Importantly, RET expression in breast cancer is also correlated with resistance to endocrine therapies via stimulation of the mTOR signaling pathway." (PMID 30666215, 2018). "However, RET is itself transcriptionally activated by ERα and is highly abundant in endocrine sensitive ER+ breast cancer cell models." (PMID 29608602, 2018). "That RET alterations are sensitive to RET inhibitors, as demonstrated in vitro and in vivo models as well as in a patient, suggest that they are potentially actionable in the subset of breast cancers in which they are found." (PMID 30446652, 2018).
breast carcinoma (continued). "Here, the AUs identify RET gene alterations, including known fusions, novel fusions, and rearrangements in breast cancer (BC) that are involved in the tumorigenic process and show the benefit of RET therapy in a recurrent BC patient carrying the NCOA4-RET fusion." (PMID 30446652, 2018). "However, addition of a RET inhibitor to treatment of an ER+/HER2 treatment-refractory, NCOA4-RET- positive breast cancer resulted in a clinical response." (PMID 30446652, 2018). "Indeed, we find that expression of RET and GFRα1 are both highest in ER+ breast cancers, likely because of direct transcriptional activation of both genes by E2/ ERα." (PMID 29608602, 2018). "Subsets of genomic alterations in RET were enriched in breast cancer subtypes." (PMID 30446652, 2018). "There was a trend toward more RET rearrangements being found in ER− breast cancers." (PMID 30446652, 2018). "Our findings may also have clinical implications in subtypes of breast cancers which also have elevated expression levels of the wild type RET protein." (PMID 28460442, 2017). "To further deepen into such an association, we sought to verify whether tumors assessed were RET-expressing and to compare RET levels in the breast cancer tissues of the different genotype groups." (PMID 27034161, 2016). "Indeed, RET inhibition was shown to increase the efficacy of antiestrogen drugs, and combined therapy of tamoxifen with vandetanib was proven as a potential treatment strategy for RET positive luminal breast cancers." (PMID 27034161, 2016). "As a consequence, there remains a need for selective RET inhibitors that could be of potential clinical application in breast cancer but with reduced toxicity." (PMID 27602955, 2016). "These genes (COL9A1, ITGB8, ITGB6, TTYH1, RET, etc.)enriched in the cell adhesion may serve as important indicators of different types of breast cancer." (PMID 26273658, 2015). "This is supported by clinical data among high RET expressing breast cancers." (PMID 24466333, 2014). "SPP86 also inhibited RET signaling in MCF7 breast cancer cells." (PMID 25409876, 2014). "Also, 7 genes (CTGF, ESR1, MAPK3, PIK3R3, PLAU, PRNP, and RET) were reported to be highly relevant to growth (P<1E-04) and microtubule dynamics (P<4E-05) in tumor cell lines, and apoptosis in breast cancers (P<1E-04)." (PMID 23185353, 2012). "Activation of RET stimulates MCF-7 breast cancer cell proliferation, survival and scattering." (PMID 21978374, 2011). "Potentially actionable molecular alterations include agnostic targets (NTRK1-2-3, RET fusions, BRAF V600E mutations, microsatellite instability, high tumor mutational burden), or tissue-specific targets, such as EGFR mutation in NSCLC or PIK3CA mutations in breast cancer." (PMID 39766151, 2024). "While these findings have yet to be reproduced, the report of an association between RET expression and HER2-positive Luminal B tumors, in combination with this initial functional characterization, suggest that RET may be a useful target in multiple subtypes of breast cancer." (PMID 36918928, 2023). "While few studies have utilized specific RET overexpression to date, we expect that the employment of such models, combined with the availability of highly specific and potent RET inhibitors, will enhance the precision of future in vitro and in vivo research related to RET in breast cancer." (PMID 36918928, 2023). "The evidence presented here supporting the efficacy of RET-selective inhibitors, taken with the well-documented effects of RET signaling on multiple breast cancer phenotypes and clinical outcomes, highlights an emerging need to expand the study of RET as a specific target in breast cancer." (PMID 36918928, 2023).